PPARG (peroxisome proliferator activated receptor gamma)
Diseases named in the same sentence as PPARG in open-access papers (continued):
Sharing a sentence is not in itself a finding about the gene and the disease.
Insulin resistance (continued). "Thiazolidinedione (TZD), a high-affinity synthetic ligand for PPARG, has been demonstrated to improve insulin resistance, reduce proteinuria and ameliorate renal function in diabetic nephropathy." (PMID 36213291, 2022). "Activation of PPARγ systemically decreases the insulin resistance while PPARα reduces both plasma cholesterol levels and insulin resistance in the body." (PMID 36302045, 2022). "PPARγ activators are used as insulin sensitizers in order to improve insulin resistance in diabetic patients." (PMID 36501129, 2022). "Excessive SUMOylation of PPARγ induces insulin resistance and vascular endothelial dysfunction along with an endogenous cascade that intensifies that reaction." (PMID 36551260, 2022). "Of interest, genes related to insulin resistance, PPARG and FASN, were KDs for both the HDL and TG subnetworks." (PMID 33561811, 2021). "More specifically, PPAR-γ activation in skeletal muscle can have an important protective effect on glucose homeostasis and insulin resistance, because muscle cells secrete functional adiponectin in a PPARγ-dependent manner, improving insulin sensitivity." (PMID 33918414, 2021). "Because of its essential role in regulating adipogenesis and higher expression in the WAT, PPARγ has been a pharmacological target for drug development in combating metabolic diseases such as insulin resistance and type 2 diabetes." (PMID 34128467, 2021). "In the present study, we have shown that PPARG hypermethylation was the first epigenetic modification observed in adipocytes following insulin resistance induction as soon as 48 h after IR induction." (PMID 34207541, 2021). "With the aggravation of inflammation, many inflammatory cytokines are released to exacerbate insulin resistance and lipolysis, reduce the activity of peroxisome proliferator-activated receptor γ (PPARγ), and accelerate the fat cell death and inflammation." (PMID 34299610, 2021). "PPARγ can regulate lipid metabolism, improve insulin resistance, suppress the transformation of macrophages into foam cells and their deposition on the blood vessel wall." (PMID 34658891, 2021). "It has been established that PPARγ phosphorylation at Ser273 promotes insulin resistance in obese and diabetic mice, and classical PPARγ ligands such as TZDs inhibit Ser273 phosphorylation to improve insulin sensitivity." (PMID 34526909, 2021). "Inhibition of HDAC3 in adipocytes increased PPARγ acetylation and the expression of PPARγ target genes, including adipokines and adipocyte protein 2, resulting in decreased insulin resistance." (PMID 34638914, 2021). "As a result, suppressing FOXO1 signalling can protect mice from HFD-induced insulin resistance by increasing insulin sensing regulator PPARγ." (PMID 34803738, 2021). "The fact that when adjusting by leptin this favorable association of the polymorphism with insulin and HOMA emerges supports the role of PPARγ in relationship with insulin resistance already at this age." (PMID 34887761, 2021). "In the validation of pathways, key targets (INSR, PTPN1, PPARA, and PPARG) from two of the most significant pathways in pathway enrichment analysis, Insulin resistance, and PPAR signaling pathway, were selected." (PMID 34579756, 2021). "Recently, clinical trials have been performed on PPARγ agonists such as rosiglitazone, pioglitazone (thiazolidinedione) and sitagliptin and metformin combination with rosiglitazone for the management of insulin resistance in metabolic syndrome." (PMID 34679777, 2021). "Our results showed LE increased PPARγ, GLUT4 and DGAT-1 levels, demonstrating the potential of this lemon extract in the management of insulin resistance conditions associated with TNF-α pathway activation." (PMID 34361563, 2021). "Several rare PPARγ variants have been reported as causes of familial partial lipodystrophy (FPLD3, OMIM 604367), insulin resistance, diabetes, and hypertriglyceridemia." (PMID 34764936, 2021).
Insulin resistance (continued). "Another notable example is how PPARγ agonists have been used as a therapeutic drug for increasing insulin resistance in diabetic patients as well as lipid metabolism in patients with atherosclerosis." (PMID 35003101, 2021). "In adipose tissue, genes important for insulin resistance and diabetes such as PPARG and FASN were found to be KDs for TG, further supporting the connection between TG and diabetes." (PMID 33561811, 2021). "Activators of both PPARα and PPARγ have been shown to improve insulin sensitivity and normalize impaired glucose tolerance in both humans and rodent models of insulin resistance." (PMID 34899310, 2021). "On the other hand, the PPARG promoter was hypermethylated at both time points, which increased as insulin resistance developed from a two-fold increase after 48 h (p = 0.032) to a triple increase after 72 h (p = 0.010)." (PMID 34207541, 2021). "In diabetic patients, lipid metabolism is disordered, PPARγ also plays an important role in the regulation of lipid metabolism, with decreased expression in insulin resistance." (PMID 34026064, 2021). "Impairment of PPARγ action results in insulin resistance and hypertension in both animal models and humans, and perhaps is a common denominator linking insulin resistance and salt sensitive hypertension in the population." (PMID 34966295, 2021). "Given the regulatory roles of Pparγ in diabetes, the identification of Pparγ inducers from herbal products and the further isolation of bioactive compounds can be useful for treating insulin resistance." (PMID 33804020, 2021). "Thiazolidinediones (TZDs) decrease hepatic and peripheral insulin resistance directly through activation of the nuclear hormone receptor PPARγ and have a well-documented effect of improving hyperglycemia and dyslipidemia." (PMID 34407851, 2021). "It has been reported that gallic acid attenuates insulin resistance via partial agonism of PPARγ and activates GLUT4 translocation by PI3K/p-Akt signaling pathway." (PMID 34394985, 2021). "PPARγ expression in ILC2s likely has some role to play in this development of insulin resistance and disease due to its regulatory role of metabolism and cell activation." (PMID 34489979, 2021). "Previously, we have clarified that CMHX008 displayed moderate PPARγ agonist activity, as it improved insulin resistance and had a lower effect on promoting preadipocyte differentiation and bone loss than rosiglitazone." (PMID 34305596, 2021). "Here, we observed elevated levels of PPARγ in the livers of fetuses exposed to BPA that at the same time experienced insulin resistance." (PMID 32623698, 2021). "TNF-α promotes insulin resistance by directly suppressing activities of insulin-induced insulin receptor substrate-1 and peroxisome proliferator-activated receptor gamma (PPAR-γ)." (PMID 35056068, 2021). "Pioglitazone is a synthetic PPARγ agonist used to lower blood glucose levels and lipotoxicity by modifying insulin resistance." (PMID 34593018, 2021). "Mice with macrophage specific deletion of PPARγ exhibit disruption of M2 macrophage activation, and development of diet induced obesity and whole-body insulin resistance." (PMID 34966295, 2021). "SERPINE1 has been reported to be related to adipocyte differentiation, and inhibition of the SERPINE1 in 3T3-L1 adipocytes can increase the expression of PPARγ, promote adipocyte differentiation, and decrease insulin resistance." (PMID 34090334, 2021). "Peroxisome proliferator activated receptor gamma (PPARγ) activity can prevent insulin resistance by increasing glucose uptake in adipocyte and muscle cells, which results in lowering of blood glucose levels." (PMID 34827690, 2021). "Curcuminoids and essential oils of turmeric have been identified as agonists for peroxisome proliferator–activated receptor-gamma (PPAR-γ) and can lower insulin resistance." (PMID 34353691, 2021).
Insulin resistance (continued). "The PPARγ agonists pioglitazone and rosiglitazone are widely used to ameliorate insulin resistance in patients with type II diabetes." (PMID 34310946, 2021). "Kaempferol, β-sitosterol, and sesamin can enhance insulin resistance, protect myocardial cells from injury, and prevent hyperlipidemia by increasing the expression of PPARG." (PMID 34211564, 2021). "Based on the pathway enrichment analysis, targets (INSR, PTPN1, PPARA, PPARG) from two of the most significant pathways, Insulin resistance, and PPAR signaling pathway, were selected for further experimental validation." (PMID 34579756, 2021). "Regarding its actions to increase insulin sensitivity, PPARγ agonists can also counteract the effects of insulin resistance on blood pressure." (PMID 34966295, 2021). "Targeting PPARγ can relieve insulin resistance and promote adipogenesis, which makes the role of PPARγ self-contradictory in the treatment of T2D." (PMID 34740314, 2021). "For that reason, targeting PPARγ activity in patients with type 2 diabetes and pre-diabetic insulin resistance is considered as a potential therapeutic strategy." (PMID 33536069, 2021). "Hepatocytes also express PPARγ, and such expression increases with insulin resistance and in nonalcoholic fatty liver disease (NAFLD)." (PMID 32963510, 2020). "Cdk5 has been shown to induce the phosphorylation of peroxisome proliferator-activated receptor γ (PPARγ) and, subsequently, to stimulate its transcriptional activity, being involved in adipogenesis and insulin resistance." (PMID 33291667, 2020). "Herein, we showed that 10- and 12-(Z,E)-HODEs induce PPARγ activation, which contributes to improving blood glucose levels by suppressing insulin resistance and inflammation, even in preadipocyte 3T3-L1 cells." (PMID 32266936, 2020). "Adipose tissue has been suggested to be a major source of circulating exosomal miRNAs in obese states, and adipocyte‐derived exosomal miR‐27a was confirmed to result in insulin resistance in skeletal muscle by targeting PPARγ." (PMID 32578911, 2020). "Natural endogenous ligands have not yet been identified, but chemical ligands/activators such as thiazolidinediones (for example, rosiglitazone) are potent activators of PPARγ and have been used in a clinical setting for the treatment of insulin resistance." (PMID 33171828, 2020). "TNFα inhibits PPARγ activity and consequently leads to suppression of adipocyte differentiation and several conditions including insulin resistance." (PMID 32524217, 2020). "Insulin resistance is a hallmark of NASH, hence insulin sensitizers, such as PPARγ agonist thiazolidinediones (TZDs) and metformin, have shown efficacy in rodent models of NASH-HCC." (PMID 32443737, 2020). "TZDs activate PPARG, whose natural ligands are free fatty acids, and also decrease insulin resistance." (PMID 32894083, 2020). "In obese insulin-resistant rats, Rg3 increased the PPARγ protein level and adenosine monophosphate-activated protein kinase (AMPK) phosphorylation in the liver." (PMID 32161549, 2020). "who used PPARγ agonists to restore the whole body insulin resistance of HFD mice that expressed PPARγ in an adipocyte-specific manner as efficiently as mice that expressed PPARγ systemically." (PMID 31918918, 2020). "In mouse experiments, the mice fed with a high calorie diet (ligand stimulation) show lower PPARG concentrations in their adipose tissues, indicating a significant protective effect pertaining to insulin resistance." (PMID 32604723, 2020). "Subjects showing the PPARG Pro12Ala C/C genotype with a BMI > 30 kg/m2 tend to have higher blood glucose values and insulin resistance; thus, BMI is potentially a modifying factor in the interaction." (PMID 32604723, 2020). "Worth highlighting here in the context of PPARγ is the role of WAT in proper glucose homeostasis, as attested by the association of lipodystrophy with severe insulin resistance." (PMID 32708786, 2020).
Insulin resistance (continued). "The link between BMPR2 dysfunction and insulin resistance is thought to bemediated by PPARγ, a downstream target of BMPR2." (PMID 32999709, 2020). "Pioglitazone and rosiglitazone, known as thiazolidinediones (TZDs), activating peroxisome proliferator-activated receptor gamma (PPARγ), reduce the extent of insulin resistance and improve β-cell response towards altered glucose levels." (PMID 32566682, 2020). "It is known that knockdown of PPARγ compromises adipose tissue function, accompanied by insulin resistance, inflammation, angiogenesis, and fibrosis." (PMID 33198073, 2020). "While insulin resistance in adipocytes increases lipolysis, there is simultaneous downregulation of transcription factors, such as PPARγ, ChREBP and FOXO1, which regulate the expression of genes necessary for TG biogenesis." (PMID 32443737, 2020). "One of the factors that can affect CKD, as well as insulin resistance, is the functioning of peroxisome proliferator-activated receptor gamma (PPARG)." (PMID 32604723, 2020). "Mice with heterozygous, tissue-specific or conditional PPARγ KO are lipodystrophic with insulin resistance and dyslipidimia." (PMID 33233602, 2020). "Antrodan elevated the level of adiponectin and suppressed that of PPARγ and SREBP-1c, thereby inhibiting the lipid biosynthesis and promoting obese- and steatohepatitis-associated insulin resistance." (PMID 31935815, 2020). "As a circadian upstream factor of SIRT1, NAMPT is involved in insulin resistance through PPARγ and adiponectin." (PMID 32334629, 2020). "Tumor necrosis factor and free fatty acids are involved in the development of insulin resistance, and then the activation of PPARγ contributed toward down-regulation of both parameter and increased the insulin sensitivity." (PMID 32815547, 2020). "As PPARγ is involved in adipogenesis, reduction in the transcription of PPARγ decreases lipid uptake and improves insulin resistance and inhibition of glucose production." (PMID 31947684, 2020). "Heterozygous PPARγ-null mice exhibited greater insulin sensitivity than wild-type littermates and were protected from the development of insulin resistance and glucose intolerance mediated by a HFD." (PMID 33348802, 2020). "Pioglitazone is a peroxisome proliferator-activated receptor gamma (PPAR-γ) agonist which can reduce insulin resistance in liver, muscle and adipose tissue and improve glucose and lipid metabolism." (PMID 32500011, 2020). "TZDs form a class of PPARγ agonists that reverse insulin resistance in liver and peripheral tissues, reducing plasma glucose through specific PPARγ activation." (PMID 32708786, 2020). "More recently, post translational modifications, such as PPARγ phosphorylation at Ser273 by CDK5 in adipose tissue, have been linked to insulin resistance trough the dysregulation of expression of a specific subset of genes." (PMID 33329381, 2020). "On the other hand, adipose-specific PPARγ knockout causes insulin resistance in the fat and liver, and these animals are more susceptible to HFD-induced insulin resistance and steatosis." (PMID 32351670, 2020). "The regulation of insulin resistance in WAT by PPARγ is accompanied by alterations of several components of insulin signaling and is often co-regulated." (PMID 31614949, 2019). "Liver-specific disruption of PPARγ in diabetic mice dramatically decreased hepatic triglyceride and systemically aggravated insulin resistance." (PMID 31121839, 2019). "In adipose tissue and skeletal muscle, rutin has been shown to increase expression of PPARγ, which further improve insulin resistance, affect insulin sensitivity, and improve glucose uptake." (PMID 30800211, 2019). "Rosiglitazone is prescribed to reduce insulin resistance in patients with type 2 diabetes, as PPARγ is an important regulator of lipid and glucose metabolism." (PMID 30682837, 2019). "Nevertheless, PPARγ is still an important target for the treatment of hyperlipidemia, insulin resistance, and diabetes mellitus." (PMID 31019978, 2019).
Insulin resistance (continued). "The Peroxisome Proliferator-activated Receptor gamma (PPARγ) is a ligand-modulated nuclear transcription factor and a therapeutic target for treating insulin resistance in type-2 diabetes patients." (PMID 30930764, 2019). "Previous study has shown that thiazolidinediones (TZDs) improved endothelium insulin resistance (IR) induced by high glucose concentration (HG)/hyperglycaemia through a PPARγ‐dependent‐NFκB trans‐repression mechanism." (PMID 30398029, 2019). "PPARγ also improves insulin resistance by promoting alternative macrophage activation, as demonstrated by the lower insulin sensitivity of macrophage-specific PPARγ knockout (KO) mice compared to that of wild-type mice." (PMID 30804707, 2019). "Thiazolidinedione (PPARγ agonist) is used to improve circulating glucose levels and insulin resistance in diabetic patients, but it was pushed back to an optional second-tier drug for unwanted adverse effects." (PMID 31019978, 2019). "Several major functions of PPARγ include uptake and safe deposition of lipids in adipose tissue, liver, and muscle; regulation of adipocytokine secretion; and improving insulin resistance." (PMID 30658440, 2019). "Our data suggest that MSCs combined with decitabine can more effectively alleviate insulin resistance and prolong and enhance the anti-diabetic effect of MSCs in T2D mice in part by prompting M2 polarization in a PPARγ-dependent manner." (PMID 31426846, 2019). "Activation of the PPARγ signaling pathway improves insulin resistance, dyslipidemia, adipokine secretion, inflammation, cell proliferation and hepatic steatosis." (PMID 30850637, 2019). "For example, we have found here that the HFHS diet causes an immediate decrease in the expression of ileal CB2, suggested to play a protective role against insulin resistance and inflammation, and of the insulin-sensitizing receptor PPARγ." (PMID 31848310, 2019). "Among them, PPARγ has been shown to ameliorate insulin resistance and regulate adipocyte differentiation." (PMID 31466366, 2019). "PPARγ is expressed in adipose tissue, immune cells, and the colon, and it is mainly responsible for regulating adipocyte differentiation and improving insulin resistance." (PMID 31336903, 2019). "PPARγ selective agonist agent- rosiglitazone improves the insulin resistance and concomitantly also showed decrease in proteasome proteolytic activity." (PMID 30647761, 2018). "Most studies have focused on the beneficial role of PPARγ in preventing many cardiovascular disorders, such as insulin resistance, ATH, hypertension, ischemia/reperfusion (I/R) injury, and dyslipidaemia." (PMID 30622558, 2018). "Since it is known that PPARγ agonists decrease insulin resistance in type II diabetes, the beneficial effects of PPARγ agonists in AD mice indicate that they can act in the same manner in CNS." (PMID 29949869, 2018). "Accordingly, PPARγ deletion or inactivation prevented anti-inflammatory polarization of macrophages and thus resulted in insulin resistance and glucose intolerance." (PMID 30111834, 2018). "As well as phosphorylating PPARγ at Ser273, leading to insulin resistance, the MEK/ERK pathway is a major regulator of energy expenditure and inflammation." (PMID 29160030, 2018). "Specifically, thiazolidinediones (TZDs), such as rosiglitazone and pioglitazone, are specific PPARγ activators and are used as insulin sensitizers in order to improve insulin resistance in T2DM patients." (PMID 29747466, 2018). "For this reason, more studies are necessary to elucidate the potential of PPARγ agonism to overcome defects in pregnancy related to insulin resistance and GDM." (PMID 30037087, 2018). "PPARG is involved in lipid and glucose homeostasis, decreased plasma leptin level, and insulin resistance." (PMID 29495392, 2018). "Mice with PPARγ knockout in mature cells also develop insulin resistance and hyperlipidemia through dysregulation of molecular pathways of insulin signaling, FFAs uptake, and lipolysis." (PMID 30037087, 2018).